IL17F (interleukin 17F)
Diseases named in the same sentence as IL17F in open-access papers (continued):
Sharing a sentence is not in itself a finding about the gene and the disease.
Chagas disease (1 paper, 2017). A parasitic infection caused by Trypanosoma cruzi. "The aim of this study was to investigate possible associations between genetic polymorphisms of IL17A G197A (rs2275913) and IL17F T7488C (rs763780) with Chagas Disease (CD) and/or the severity of left ventricular systolic dysfunction (LVSD) in patients with chronic Chagas cardiomyopathy (CCC)." (PMID 28470012, 2017).
cholestasis (1 paper, 2017). Impairment of the bile flow caused by obstruction within the liver, or outside the liver in the bile duct system. "Abnormal expression of IL-6, IL-10, IL-17A, IL-17F, TGF-β1 and α-SMA are closely associated with the cholestasis." (PMID 28646179, 2017).
Chronic colitis (1 paper, 2024). A chronic inflammatory disease of the large intestine (colon, cecum and rectum). "Both cytokines have a redundant but unequal pathogenic role in gut inflammation and balanced inhibition of IL-17A and IL-17F represents promising goal for therapy development in chronic colitis." (PMID 39354587, 2024).
chronic lung infection (1 paper, 2020). "Th17 lineage cytokines (IL-17A, IL-17F, and IL-22) and chemokines (CXCL1, CXCL2, CXCL5, and CXCL8) are known to control chronic lung infection caused by mycobacteria." (PMID 33520738, 2020).
chronic pancreatitis (1 paper, 2022). A chronic inflammatory process causing damage and fibrosis of the pancreatic parenchyma. "IL-17F was decreased in patients with pancreatic adenocarcinoma compared with chronic pancreatitis patients." (PMID 35012470, 2022).
coccidiosis (1 paper, 2019). A parasitic infection caused by Coccidia. "Moreover, our previous studies have indicated that Th17-related cytokines such as IL-17A and IL-17F, and IL-17 receptor signaling are involved in inflammation induced by coccidiosis, although the predominant protective response in coccidiosis is considered to be an IFN-γ-related Th1 response." (PMID 30972060, 2019).
colorectal tumors (1 paper, 2016). "Even though IL-17F is strongly expressed in the colon by activated T cells and colonic epithelial cells, IL-17F is downregulated in colorectal tumors." (PMID 27148488, 2016).
Constipation (1 paper, 2021). Infrequent or difficult evacuation of feces. "We found the reduced levels of TGF-β, IL-10, and IL-21, and the increased levels of GM-CSF, IL-17A, IL-17F, IL-22, and IL-23 in the serum of constipation EAE mice." (PMID 34301274, 2021). "We found that the concentrations of TGF-β, IL-10, and IL-21 were decreased while the levels of GM-CSF, IL-17A, IL-17F, IL-22, and IL-23 were increased in constipation EAE mice and FMT EAE mice compared to EAE mice." (PMID 34301274, 2021). "Moreover, the serum levels of TGF-β, IL-10, and IL-21 were decreased while the GM-CSF, IL-17A, IL-17F, IL-22, and IL-23 were increased in the constipation EAE mice." (PMID 34301274, 2021).
cyst (1 paper, 2026). A sac-like closed membranous structure that may be empty or contain fluid or amorphous material. "Immunized animals showed significant reductions in intestinal trophozoite burden and faecal cyst shedding at 7, 14, and 21 days post-infection, accompanied by increased serum IL-17F and IL-22." (PMID 42290664, 2026).
dengue (1 paper, 2020). "Whereas in secondary cases IL-17A was associated with dengue severity, there was no such association for IL-17F." (PMID 33322218, 2020).
depression (1 paper, 2020). "IL-17, a pro-inflammatory cytokine, is a member of the cytokine family comprising IL-17A, IL-17B, IL-17C, IL-17D, IL-17E (IL-25) and IL-17F and it was found before, to be elevated in the serum of patients suffering from depression." (PMID 33322667, 2020).
disc degeneration (1 paper, 2025). "Notably, IL-4 also triggered a substantial upregulation of the pro-inflammatory cytokine IL-17F, implicating a previously unrecognized role for IL-4 in reinforcing inflammatory circuits that may potentiate disc degeneration under pathological conditions." (PMID 40421015, 2025).
disseminated candidiasis (1 paper, 2009). Systemic candidiasis occurs when Candida yeast enters the bloodstream and may spread (becoming disseminated candidiasis) to other organs, including the central nervous system, kidneys, liver, bones, muscles, joints, spleen, or eyes. "The lack of a requirement for IL-17A to mediate normal host defense against disseminated candidiasis likely reflects the ability of IL-17F, which also activates the common IL-17 receptor, to complement an IL-17A deficiency." (PMID 20041174, 2009).
E. coli infections (1 paper, 2015). "Another major issue concerns the characterization of the cells that overexpress the genes for IL-17A and IL-17F upon E. coli infection." (PMID 26062913, 2015).
encephalitis (1 paper, 2018). An acute inflammatory process affecting the brain parenchyma. "IL-17F and CXCL1 CSF concentrations correlated with neutrophil count and CXCL1 concentration was higher in patients with encephalitis." (PMID 29678185, 2018).
endometriosis (1 paper, 2022). The growth of functional endometrial tissue in anatomic sites outside the uterine body. "And another member of the IL-17 family, IL-17F, had a similar function in stimulating the secretion of IL-8 and the expression of COX2 in ESCs and it is speculated IL-17F may promote endometriosis through these mechanisms." (PMID 35582411, 2022).
enteritis (1 paper, 2025). Inflammation of the small intestine. "Increased expression of other Th17 cytokines in A20ZF7 mouse intestines, e.g., IL-17F and/or IFN-γ, may also contribute to enteritis in these mice." (PMID 40892518, 2025).
enterocolitis (1 paper, 2024). An inflammatory process affecting the small intestine and colon. "IL-17f was associated with both dermatologic and enterocolitis irAEs, while IL-25 was elevated in enterocolitis irAEs (P < 0.05)." (PMID 39403935, 2024).
food allergy (1 paper, 2021). Gastrointestinal disturbances, skin eruptions, or shock due to allergic reactions to allergens in food. "Our results suggest that epigenetic modification of the IL17F gene is associated with food allergy." (PMID 33571165, 2021). "It has been suggested that IL-17A plays a role in the regulation of food allergy and is a potential biomarker of tolerance to food allergens; however, the role of IL-17F in food allergy is not well understood." (PMID 33571165, 2021).
gout (1 paper, 2016). A condition characterized by painful swelling of the joints, which is caused by deposition of urate crystals. "The present study evaluated the association between IL-17A rs2275913, IL-17F rs763780, and IL-17RA rs4819554 single nucleotide polymorphisms (SNPs) as well as serum concentrations of IL-17A and IL-17F with gout susceptibility in a male Chinese Han population." (PMID 26890073, 2016). "We speculate that IL-17A and IL-17F together play a role in gout pathogenesis, which needs further investigation." (PMID 26890073, 2016).
granulocytopenia (1 paper, 2017). "Furthermore, higher levels of IL-17F were found in patient groups with neutropenia, granulocytopenia, and increased ESSDAI, which indicated that IL-17F was associated with pSS disease activity and severity." (PMID 28210632, 2017).
immunodeficiency disease (1 paper, 2022). Disease in which there is a deficiency or defect in the mechanisms of immunity, either cellular or humoral. "The most frequently reported monogenic immunodeficiency disease that causes IC and CNSC is Caspase Recruitment Domain Family Member 9 (CARD9) defects, followed by Autoimmune Regulator (AIRE), Signal Transducer And Activator Of Transcription 1 (STAT1), STAT3, and Interleukin 17F (IL17F) defects." (PMID 36526986, 2022).
intestinal cancer (1 paper, 2022). "This was also associated with reducing IL-1β, Cox-2, and IL-17RC expression suggesting proinflammatory and protumorgenic roles of IL-17F in intestinal cancer." (PMID 35012470, 2022). "On the other hand, Chae and Bothwell used ApcMin/+ mice model highly susceptible to develop spontaneous intestinal adenoma to study the effect of IL-17F on intestinal cancer." (PMID 35012470, 2022).
intestinal tumor (1 paper, 2016). "Furthermore, Il17f-deficient mice developed more and larger intestinal tumors compared with WT animals in the AOM/DSS model of CAC." (PMID 27148488, 2016). "Il17ra−/− animals, which are insensitive to IL-17A and IL-17F, show reduced intestinal tumor number, size, and load during sporadic CRC." (PMID 27148488, 2016).
lymph node metastasis (1 paper, 2012).
lymphoma (1 paper, 2022). A malignant (clonal) proliferation of B- lymphocytes or T- lymphocytes which involves the lymph nodes, bone marrow and/or extranodal sites. "In six articles, the expression of IL-17F in lymphomas was evaluated." (PMID 35012470, 2022).
meningococcal meningitis (1 paper, 2025). "In meningococcal meningitis, antibodies targeting IFN-γ (10%), IL-1α (7%), and IL-17F (7%) were associated with infection, while antibodies against IFN-γ were more prevalent in viral meningoencephalitis (12%)." (PMID 41161094, 2025). "Patients with meningococcal meningitis had a higher prevalence of anti-IFN-γ (9 of 86 [10%] vs. 3 of 264 [1%], p = 0.004), anti-IL-1α (6 of 86 [7%] vs. 1 of 264 [0%], p = 0.015), and anti-IL-17F (6 of 86 [7%] vs. 1 of 264 [0%], p = 0.015) compared to controls." (PMID 41161094, 2025).
metabolic syndrome (1 paper, 2022). A cluster of metabolic risk factors for CARDIOVASCULAR DISEASES and TYPE 2 DIABETES MELLITUS. "The level of IL-17F is suppressed by the high content of potassium, iron, vitamin B6, folic acid and vitamin C in the diet, which makes it possible to carry out appropriate supplementation or diet therapy in people at risk of metabolic syndrome." (PMID 35277002, 2022). "The excess of adipose tissue is a factor predisposing to metabolic syndrome, which could result in cardiovascular diseases, and the level of IL-17F is associated with atherosclerotic processes." (PMID 35277002, 2022).
metastatic tumors (1 paper, 2013). "Significantly higher levels of the pro-osteoclastogenic cytokines IL-17F,RANKL, IL-1β, TNFα, and IL-6 were detected in the sera and supernatants fromLN-stimulated cells of animals bearing the metastatic tumors than in mice withnon-metastatic tumors." (PMID 23935856, 2013).
necrotizing enterocolitis (1 paper, 2019). Necrotizing enterocolitis (NEC) is a devastating disease that affects mostly the intestine of premature infants. "Beside RA, IL17A (rs2275913) polymorphism has been reported to be associated with the development of rheumatic heart disease in south Indian population, and a variant of IL17F (rs763780) may contribute to the development of necrotizing enterocolitis." (PMID 30658595, 2019).
obstetric disorder (1 paper, 2025). Disorder associated with pregnancy, childbirth, and puerperium. "Th17 cells contribute to successful pregnancy outcomes through the secretion of IL-17A and IL-17F, having also been implicated in the pathophysiology of obstetric disorders." (PMID 40894398, 2025).
Oropharyngeal Cancer (1 paper, 2020). Carcinoma, predominantly squamous cell, arising from the epithelial cells of the oropharynx. "The aim of this study was to assess levels of IL-17A, IL-17E/IL-25, IL-17F, and TNF-α in the saliva in patients with oral and oropharyngeal cancer, depending on the degree of malignancy and bacteriological cultures from the oral cavity as potential biomarkers of cancer." (PMID 32855976, 2020).
osteosarcoma (1 paper, 2023). A usually aggressive malignant bone-forming mesenchymal neoplasm, predominantly affecting adolescents and young adults. "Microarray analysis revealed that osteosarcoma samples from patients exhibited a higher IL-17RA expression relative to either IL-17A and IL-17F." (PMID 38062130, 2023).
palmoplantar pustulosis (1 paper, 2025). A rare skin disease characterized by chronic eruption of sterile pustules on an erythematous and desquamative background, affecting the palms and soles, sometimes also the lateral aspects of hands and feet. "A unique subset of Th17 cells with regulatory phenotype drives inflammation in palmoplantar pustulosis by producing IL-17F and IL-26 and interacting with inflammatory keratinocytes." (PMID 40985896, 2025).
relapsing-remitting multiple sclerosis (1 paper, 2017). The most common clinical variant of multiple sclerosis, characterized by recurrent acute exacerbations of neurologic dysfunction followed by partial or complete recovery. "Overexpressed IRF4 in naive CD4+ T cells derived from relapsing remitting multiple sclerosis patients significantly increased their ability to secrete IL-17A, IL-17F, IL-21, and IL-22." (PMID 28808358, 2017).
rosacea (1 paper, 2023). A chronic erythematous skin disorder that affects the face. "Adaptive T cell–derived cytokines IFNG, IL17A, IL17F, and IL22 were significantly overexpressed in lesional rosacea skin, while IL4 was either undetectable or not increased." (PMID 36633910, 2023).
sarcoidosis (1 paper, 2022). Sarcoidosis is a multisystemic disorder of unknown cause characterized by the formation of immune granulomas in involved organs. "Levels of Th17 (IL17-A, IL17-F) and Th2 (IL-4, IL-13) cytokines tended to be less abundant in sarcoidosis patients relative to controls." (PMID 35668129, 2022).
Sézary syndrome (1 paper, 2016). "Both, IL-2 and IL-15 reportedly promote growth and viability of CTCL and Sézary syndrome derived cell lines, while co-expression of IL-15 and IL-17F characterizes mycoses fungoides." (PMID 27144517, 2016).
silicosis (1 paper, 2024). Silicosis is a respiratory disease caused by breathing in (inhaling) silica dust. "Miaoet al.30 also found that TNFligand superfamily 4 isoform X1 (TNFSF4), IFN-β precursor, IL-6, atypicalchemokine 2 receptor, and mutant IL-17F were all upregulated in exposed patients,both with and without silicosis." (PMID 39606764, 2024).
Strongyloides infection (1 paper, 2021). "A diminution in mycobacterial-specific Th1 cells and Th17 cells and their relevant cytokines (i.e., IFN-γ, TNF-α and IL-2, IL-17A, and IL-17F) has been found in patients with concomitant filarial or Strongyloides infection." (PMID 34202662, 2021).
Systemic Amyloidosis (1 paper, 2024). "In the present study, inhibition of IL-17A was significantly effective against systemic amyloidosis, whereas inhibition of IL-17F was not." (PMID 39519167, 2024).
tendinopathy (1 paper, 2021). "However, in combination with TNF-α, all three IL-17 cytokines induce similar levels of IL6 and MMP3 mRNA expression, which could make not only IL-17A, but also IL-17F and IL-17AF interesting treatment targets in tendinopathy." (PMID 35004653, 2021).
tick-borne encephalitis (1 paper, 2018). Tick-borne encephalitis is caused by an arbovirus of the Flaviviridae family (tick-borne encephalitis virus, TBEV), transmitted principally by the bite of the Ixodes ricinus tick. "Concentrations of IL-17A, IL-17F, IL-22, CXCL1, and CXCL2 in serum (S) samples obtained from tick-borne encephalitis patients on admission to hospital are shown horizontal axes and in cerebrospinal fluid (CSF) samples obtained simultaneously on vertical axes (expressed in pg/ml)." (PMID 29678185, 2018).
triple-negative breast carcinoma (1 paper, 2020). An invasive breast carcinoma which is negative for expression of estrogen receptor (ER), progesterone receptor (PR), and human epidermal growth factor receptor 2 (HER2). "A recent study reported elevated levels of Th17 cell cytokines (IL-17A and IL-17F) in T cell non-inflamed triple-negative breast cancer; thus, IL-17 was proposed as a novel prognostic biomarker for this type of cancer." (PMID 32225066, 2020).
vaginal candidiasis (1 paper, 2013). "Thus, confirming recent findings, the neutrophil response in vaginal candidiasis occurs independently of IL-22 and IL-17F." (PMID 23853597, 2013).
viral infection (1 paper, 2016). "While previous studies have demonstrated that IL-17A signaling directly induces CXCL10 production in esophageal cell lines, and the production of IL-17F is necessary for CXCL10 expression in hepatic viral infection models, whether the IL-17 axis induces CXCL10 during NAFLD remains undefined." (PMID 26895034, 2016).
ZIKV infection (1 paper, 2020). "Our results further suggest that IL-17A, but not IL-17F, specifically inhibits the expression of IFN-α2 during CHIKV, but not WNV or ZIKV infection." (PMID 33304351, 2020).